ALKBH5 (alkB homolog 5, RNA demethylase)
Diseases named in the same sentence as ALKBH5 in open-access papers (continued):
Sharing a sentence is not in itself a finding about the gene and the disease.
glioma (continued). "Having established the predominant role of FTO inhibition versus ALKBH5 inhibition in m6A hypermethylation in IDH1wt glioma cells, we employed FTO-specific small-molecule inhibitors, FB23-2 and MA, to test whether pharmacologic FTO inhibition might provide a tractable treatment strategy." (PMID 38445960, 2024). "Therefore, ALKBH5 could be a potential therapeutic target for the radioresistance and aggressiveness of gliomas." (PMID 38072944, 2023). "Therefore, we hypothesized that high ALKBH5 expression altered the immune microenvironment in the glioma tissues by modulating the expression levels of ICP receptors and ligands such as TNFRSF14, CD40, CD96, PDCD1LG2, CD70 and TNFSF14." (PMID 35444654, 2022). "Therefore, ALKBH5 is a potential immunotherapeutic biomarker for selecting tumor patients that may benefit from immune checkpoint blockade (ICB) therapy in glioma and other cancers." (PMID 35444654, 2022). "In addition, some researchers found that ALKBH5 was highly expressed in glioma cells and that silencing ALKBH5 could inhibit the proliferation of glioma cells." (PMID 35682599, 2022). "Similarly, the DNA demethylation in the promoter region of IGF2BP3 could influence the progression of G-CIMP gliomas, and cg07166550/ALKBH5 could be used as prognostic biomarkers in prostate cancer." (PMID 33718187, 2021). "Hence, we thought miR-1252-5p could directly target NANOG 3’UTR or inhibit ALKBH5-mediated demethylation to reduce NANOG expression in glioma." (PMID 33975615, 2021). "In gliomas, the expression levels of METTL3, ALKBH5, YTHDF2, and IGF2BP3 were found to be elevated compared to normal brain tissues." (PMID 38398118, 2024). "Silencing ALKBH5 suppresses FOXM1 and GSC proliferation, and its inhibitors have shown effectiveness in decreasing glioma cell proliferation." (PMID 38474421, 2024). "Recent studies have indicated that ALKBH5 and YTHDF2 are important regulators of glioma cell proliferation." (PMID 38398118, 2024). "This highlights a new role for ALKBH5 and YTHDF2 in glioma, presenting a promising target for glioma immunotherapy." (PMID 39135292, 2024). "In gliomas, orphan nuclear receptors TLX, and ALKBH5 have been described to increase PD-L1 expression." (PMID 38326861, 2024). "The m6A demethylase ALKBH5 was found to maintain the tumorigenicity of glioma stem cells by regulating FOXM1 expression 13, while, ALKBH5 promotes OS progression by upregulating PVT1." (PMID 38164289, 2024). "To elucidate the role of m6A modifiers in regulating AS of LINC00475, we initially assessed the expression levels of METTL3, ALKBH5, and FTO in glioma cells." (PMID 38405130, 2024). "Erasing the m6A methylation of glucose-6-phosphate dehydrogenase (G6PD) enhances its stability and then ALKBH5 promotes G6PD translation and activates the pentose phosphate pathway (PPP) to induce the proliferation of glioma cells." (PMID 38072944, 2023). "Several studies have found that FOXM1 level is upregulated in GSCs by ALKBH5, SATB2 and other molecular to keep glioma stemness." (PMID 37620304, 2023). "The Chinese Glioma Genome Atlas (CGGA) and The Human Protein Atlas (HPA) databases were utilized to investigate the relationship between ALKBH5 and PYCR2." (PMID 37325047, 2023). "When circ-0072083 is downregulated, the demethylation of ALKBH5 is eliminated, and the expression level of NANOG is downregulated, thus achieving the regulation of drug resistance in glioma." (PMID 35688823, 2022). "This suggested that ALKBH5 mediated the activation of ICP genes and was an ideal target for immunotherapy of glioma patients." (PMID 35444654, 2022). "Next, we analyzed ALKBH5 mRNA expression levels in different WHO grades, subtypes, and new types of gliomas." (PMID 35444654, 2022). "Next, we analyzed the correlation between ALKBH5 and various ICP receptors and ligands in glioma patients from the CGGA_325, CGGA_693, and TCGA datasets." (PMID 35444654, 2022).
glioma (continued). "In glioma stem-like cells, METTL3 and METTL14 were also shown to suppress cell differentiation, while WTAP and ALKBH5 promote cell proliferation, self-renewal, and tumorigenicity." (PMID 36293529, 2022). "To determine the role of ALKBH5 in regulating immune response, we employed two orthotopic mouse models using GL261 murine glioma cells." (PMID 36566230, 2022). "Similarly, we also found that ALKBH5 could increase NANOG expression in glioma." (PMID 33975615, 2021). "ALKBH5 directly binds with LncRNA FOXM1-AS to promote FOXM1 expression and maintain the characteristics of glioma stem cells." (PMID 32439916, 2020). "Only text mining evidence supported the interaction of ALKBH5 and FTO in the String database, and the expressions of ALKBH5 and FTO were negatively correlated with each other in gliomas." (PMID 30810537, 2019). "In addition, upregulated ALKBH5 demethylated G6PD mRNA and enhanced the stability and expression of G6PD in glioma, which activated the pentose phosphate pathway and stimulated the proliferation of glioma cells." (PMID 40001461, 2025). "High expression of ALKBH5 significantly inhibits TME immune activation and promotes glioma growth." (PMID 40469294, 2025). "ALKBH5 demethylates the G6PD transcript and enhances its mRNA stability, thereby promoting G6PD translation and activating the pentose phosphate pathway (PPP), consequently enhancing glioma cell proliferation." (PMID 40469294, 2025). "To investigate the correlation between ALKBH5 expression and GBM prognosis, we conducted a Kaplan–Meier survival analysis of two GBM datasets—one from the Chinese Glioma Genome Atlas (CGGA) and another from Nanfang Hospital (based on immunohistochemistry [IHC] staining score)." (PMID 39974663, 2025). "Additionally, the mRNA expression levels of MST4/STK26, USP14, and ALKBH5 were positively correlated with ALKBH5 target genes, including FANCD2, FANCI, MKI67, and RAD51 within the TCGA and CGGA glioma datasets." (PMID 39990235, 2025). "Thus, increased expression of ALKBH5 and decreased expression of FTO can be used to predict the poor prognosis of gliomas." (PMID 40469294, 2025). "Additionally, miR-1252-5p also serves as an inhibitor of ALKBH5, suppressing ALKBH5-mediated demethylation and thereby reducing NANOG expression in gliomas." (PMID 40469294, 2025). "Importantly, the expression levels of ALKBH5 and USP36 protein correlated with each other in the human gliomas." (PMID 38398118, 2024). "We performed selective short hairpin RNA (shRNA) knockdown experiments to further assess the possibility that FTO, rather than ALKBH5, is the main mediator of D-2-HG effects on m6A in glioma." (PMID 38445960, 2024). "ALKBH5 also promotes PYCR2 expression, influencing glioma cell proliferation, migration, and PMT." (PMID 38474421, 2024). "According to these findings, RP2 may be correlated with m6A modification in glioma, and the combined effect of METTL14, VIRMA, ALKBH5, YTHDC2 and METTL3 may eventually affect the progression and poor prognosis of glioma." (PMID 37602882, 2023). "ALKBH5 acts as a modification switch of lncRNA SOX2OT and participates in the lncRNA-mediated competitive endogenous RNA model to enhance the molecular stability and exploit the function of SOX2OT, thus affecting progression and drug resistance in glioma." (PMID 36675186, 2023). "In accordance with this, whether such regulation of Nrf2 by ALKBH5 and IGF2BP2 also has an influence on ferroptotic cell death in glioma needs to be further investigated." (PMID 37202791, 2023). "Moreover, the expression levels of ALKBH5 mRNA correlated with the WHO CNS5 types and glioma subtypes." (PMID 35444654, 2022). "ALKBH5 expression was associated with tumor grades, subtypes, and new WHO tumor types (IDH mut+codel, IDH mut+non-codel and IDH wild) in glioma." (PMID 35444654, 2022). "It was demonstrated that the inhibitory effects of MV1035 on glioma cell migration and invasion rely on ALKBH5 inhibition but not sodium channel blocking." (PMID 35063010, 2022).
glioma (continued). "In short, circ_0072083 depletion inhibited ALKBH5 expression via releasing miR-1252-5p, which further downregulated NANOG expression, thus alleviating temozolomide resistance by inhibiting the maintenance of glioma stem cells." (PMID 35843942, 2022). "In conclusion, exosomal circ_0072083 could promote TMZ resistance in glioma by increasing NANOG, possibly via regulating miR-1252-5p-mediated degradation and miR-1252-5p/ALKBH5 axis-mediated demethylation." (PMID 33975615, 2021). "Moreover, the expressions of WTAP, RBM15, YTHDF2, YTHDF1 and ALKBH5 were highly correlated with each other, and all of their expressions were negatively correlated with FTO in gliomas." (PMID 30810537, 2019). "Furthermore, an ALKBH5 inhibitor IOX1, can suppress ALKBH5 activity through a cofactor 2-oxoglutarate oxygenase competitive manner to enhance the therapeutic efficacy of anti-PD-1 treatment in preclinical glioma mice models." (PMID 40958857, 2025). "Coupled with the higher affinity of D-2-HG for FTO versus ALKBH5 at the molecular level, our experiments indicate that IDH1mut-generated D-2-HG inhibits FTO to induce m6A hypermethylation that ultimately results in the slower growth phenotype seen in IDH1mut gliomas." (PMID 38445960, 2024). "Further exploration of ALKBH5's protein distribution, interactors, and expression in GBMs reveals its presence in both the nucleus and cytoplasm of U251 GBM cells Immunohistochemistry staining images from the HPA datasets suggest higher expression of ALKBH5 in higher-grade gliomas." (PMID 38221546, 2024). "Similarly, miR‐193a‐3p could repress ALKBH5 expression, thus elevating AKT2 m6A abundance and inhibiting apoptosis in glioma." (PMID 36162823, 2023). "Specifically, ALKBH5 demethylates the transcript of glucose-6-phosphate dehydrogenase (G6PD), the rate-limiting enzyme of the pentose phosphate pathway (PPP), and enhances its mRNA stability, thus promoting oxidative PPP flux and stimulating the aggravation of glioma." (PMID 35063010, 2022). "Similarly, specific inhibitors of another m6A ‘eraser’, ALKBH5, have been tested and show efficient inhibition of GBM cell proliferation enhanced radiosensitivity and reduced invasiveness of GSCs, and improved anti-PD1 treatment efficiency in a preclinical glioma model." (PMID 36831575, 2023). "Analysis of the TCGA database and the CGGA_325, CGGA_693 datasets showed significantly higher ALKBH5 mRNA levels in the glioma patients with wild-type IDH and chromosomal 1p/19q non-codeletion, and significantly reduced in the glioma patients with MGMT promoter methylation." (PMID 35444654, 2022).
ovarian carcinoma (61 papers, 2019 to 2025). A malignant neoplasm originating from the surface ovarian epithelium. "In total, we found that mutation of ALKBH5 is only 1.5% in ovarian cancer, however, the mutation of IGF2BP2 accounts for 27% of ovarian cancer patients." (PMID 38637813, 2024). "Results represented that ALKBH5 was associated with immune response and inflammatory response in ovarian cancer." (PMID 38637813, 2024). "In this study, we have found that AlkB homolog 5 (ALKBH5) is associated with LN metastasis in ovarian cancer." (PMID 36632222, 2023). "The downregulation of FTO and ALKBH5 in ovarian cancers with breast-cancer susceptibility gene 2 (BRCA2) mutations enhanced FZD10 mRNA m6A modifications, which ultimately reduced the sensitivity of PARPi via the Wnt/β-catenin pathway." (PMID 36517820, 2022). "ALKBH5 was also suggested to contribute to resistance to PARP inhibitors in BRCA1/2-mutated ovarian cancer cell lines by regulating the expression of FZD10 mRNA and mediating the Wnt signaling pathway." (PMID 34496932, 2021). "In our current study, according to the Kaplan–Meier plotter database, when YTHDF1, YTHDF2, WTAP, FTP, and ALKBH5 were highly expressed in ovarian cancer, they were validated as valuable prognostic risk factors for low OS and PFS with high HR." (PMID 33225598, 2021). "High expression of ALKBH5 was positively associated with ovarian cancer stages (P = 0.019), node metastasis (P = 0.04), distant metastasis (P < 0.001), peritoneal seeding (P = 0.001), ascites formation (P < 0.001), primary tumor origin (P = 0.04), histological type (P = 0.037)." (PMID 38505602, 2024). "In addition, many m6A-related factors such as YTHDF2, LETM1, METL3 and ALKBH5 have also been confirmed to be associated with the malignancy of ovarian cancer." (PMID 37005667, 2023). "Indeed, previous studies have shown that the induction of ALKBH5 expression occurs in ovarian cancer tissues and is associated with tumor cell proliferation and invasion in vitro." (PMID 35251990, 2022). "They discovered that both demethylase ALKBH5 and TLR4 expression were increased, confirming that ALKBH5-mediated m6A demethylation modification activates the NF-κB pathway, which promotes the invasiveness of ovarian cancer." (PMID 39904996, 2025). "This study reveals a novel regulatory mechanism of ALKBH5 in ovarian cancer: it modifies PVT1 RNA and subsequently stabilizes FOXM1." (PMID 38098223, 2024). "In single-cell analysis, we found that ALKBH5 was mainly expressed in macrophages in ovarian cancer." (PMID 38637813, 2024). "In ovarian cancer, ALKBH5 was up-regulated to enhance the stability of BCL-2, thus inhibiting the autophagy, and promoting the invasion and proliferation of cancer cells." (PMID 38637813, 2024). "Ovarian cancer patients with higher expression of ALKBH5 and IGF2BP2 showed worse prognosis, possibly because of their close correlation with immune response." (PMID 38637813, 2024). "Taken together, our result showed that demethylase ALKBH5 is essential for FSH-induced EMT progression in epithelial ovarian cancer cells." (PMID 38505602, 2024). "TCGA data reveals the positive correlation between FSH, ALKBH5 and Snail expression in ovarian cancer." (PMID 38505602, 2024). "The results showed that ALKBH5 is widely expressed in various cells, with the highest up-regulation observed in macrophages not only in ovarian cancer, but also in ovarian tissues." (PMID 38637813, 2024). "ALKBH5 participated in regulating macrophage M2 polarization in ovarian cancer immune microenvironment." (PMID 38637813, 2024). "Our result showed FSH activates CREB to increase ALKBH5 and Snail expression, thereby enhancing migration and invasion of ovarian cancer." (PMID 38505602, 2024). "The crucial role of ALKBH5 in FSH-induced ovarian cancer metastasis was confirmed in both animal model and clinical samples." (PMID 38505602, 2024).
ovarian carcinoma (continued). "Survival analysis showed both ALKBH5 and Snail higher expression was related to shorter overall survival times in ovarian cancer patients." (PMID 38505602, 2024). "ALKBH5 has been recently reported to induce lymphatic metastasis in ovarian cancer by regulating ITGB1 expression, and antibodies that block ITGB1 are promising anti-metastatic agents." (PMID 38254031, 2024). "The expression of ALKBH5 in distinct subtypes of ovarian cancer cells was also much higher than IGF2BP2, including differentiated, immunoreactive, mesenchymal and proliferative ovarian cancer." (PMID 38637813, 2024). "The pathways that ALKBH5 correlated in ovarian cancer were also immune-related pathways, such as Th17 cell differentiation, NOD-like receptor signaling pathway and NF-κB signaling pathway." (PMID 38637813, 2024). "Our results confirmed that ALKBH5 had higher expression in epithelial ovarian cancer cell lines (e.g., SK-OV3, ES-2, and A2780) compared with the normal ovary cell line (e.g., ISOE-80)." (PMID 38505602, 2024). "In our present study, we demonstrated that ALKBH5, which is a critical RNA demethylase, is posttranscriptionally overexpressed in ovarian cancer and related cell lines." (PMID 38098223, 2024). "The abnormal expression of m6A-related regulatory enzymes including METTL3, FTO, ALKBH5, IGF2BP1, YTHDF1, and YTHDF2 is closely linked with the growth, metastasis, invasion, and chemotherapy resistance in ovarian cancer." (PMID 37781028, 2023). "We investigated the role of ALKBH5 in LN metastasis of ovarian cancer using a popliteal lymphatic metastasis model." (PMID 36632222, 2023). "In epithelial ovarian cancer, silencing of ALKBH5 promotes autophagy and inhibits the proliferation and invasion of SKOV3 cells by activating the PI3K-AKT-mTOR signaling pathway, whereas the overexpression of ALKBH5 exerts an opposite effect." (PMID 36632456, 2023). "Next, utilizing the ssGSEA algorithm and conducting overall survival analyses, we have identified the key prognosis-related immunological signatures in ovarian cancer to be ALKBH5, WTAP, ELAVL1, and CDH2 as the regulators." (PMID 37684273, 2023). "On the one hand, due to activating the EGFR-PIK3CA-AKT-mTOR signaling pathway, ALKBH5 suppressed autophagy to improve the proliferation and invasion of human ovarian cancer cells." (PMID 35628623, 2022). "In epithelial ovarian cancer cells, overexpressed ALKBH5 in human ovarian cancer (SKOV3) cells enhanced the stability of BCL-2 mRNA and inhibited tumor cell growth and metastasis." (PMID 35707365, 2022). "Recent research revealed that overexpression of FTO was accompanied by BCL-2 upregulation, which was consistent with the trend of regulation of BCL-2 by ALKBH5 found in epithelial ovarian cancer (EOC)." (PMID 36517820, 2022). "Previous studies have shown that ALKBH5 inhibits Bcl2 degradation by reducing m6A modification, thereby regulating cell apoptosis in ovarian cancer, hepatocellular carcinoma, and cerebral ischemia-reperfusion injury." (PMID 35799597, 2022). "Several studies have shown that ALKBH5 inhibits Bcl2 degradation by reducing m6A modification, thereby regulating cell apoptosis in ovarian cancer, hepatocellular carcinoma and cerebral ischemia-reperfusion injury." (PMID 35799597, 2022). "Increased ALKBH5 in ovarian cancer predicts poorer survival, as the high expression of ALKBH5 activates the mTOR and BLC2-Beclin1 pathways to promote proliferation, invasion, and even autophagy." (PMID 36360287, 2022). "ALKBH5 inhibits autophagy and promotes malignancy in ovarian cancer cells by stabilizing BCL2 mRNA and promoting BCL2 binding to BECN1." (PMID 35063010, 2022). "Previous study has shown that ALKBH5 promoted the expression of Bcl2 through regulating miR-7 in ovarian cancer." (PMID 35799597, 2022). "A study by the Zhu group proposed that ALKBH5 promoted epithelial ovarian cancer by controlling autophagy flux." (PMID 35628623, 2022).